CACUL1 (CDK2 associated cullin domain 1)
Description:
Cell cycle associated protein capable of promoting cell proliferation through the activation of CDK2 at the G1/S phase transition.
Synonyms: C10orf46; CAC1; FLJ40409; MGC33215
Tractability: PROTAC: ubiquitination databases record sites on it.
Gene: Protein-coding gene on chromosome 10 (118,674,167 to 118,755,249, reverse strand). Ensembl gene ENSG00000151893.
Subcellular location (Human Protein Atlas): Nucleoplasm
Gene Ontology:
Molecular function: protein binding; protein kinase binding; ubiquitin protein ligase binding
Biological process: G1/S transition of mitotic cell cycle; positive regulation of cell population proliferation; positive regulation of protein kinase activity; ubiquitin-dependent protein catabolic process
Genetic constraint (gnomAD): Loss-of-function variants: 5 observed, 16.36 expected, observed/expected ratio (o/e) 0.31, 90% interval 0.16 to 0.64. The upper end of that interval is the gene's LOEUF score, 0.64, which puts it in group 2 of 6, group 1 being the genes least tolerant of losing a copy. Missense variants: 256 observed, 247.08 expected, observed/expected ratio (o/e) 1.04, 90% interval 0.94 to 1.15. Synonymous variants: 118 observed, 98.51 expected, observed/expected ratio (o/e) 1.2, 90% interval 1.03 to 1.4.
Homologues: Orthologues: chimpanzee CACUL1 (99% identical), dog CACUL1 (97% identical), mouse Cacul1 (94% identical), rat Cacul1 (94% identical), guinea pig CACUL1 (90% identical), macaque CACUL1 (83% identical), pig CACUL1 (83% identical), rabbit CACUL1 (82% identical), tropical clawed frog cacul1 (65% identical), zebrafish cacul1 (40% identical). Paralogues in human: CUL4B (22% identical), CUL4A (19% identical), CUL3 (16% identical), CUL1 (16% identical), ANAPC2 (15% identical), CUL2 (13% identical), CUL5 (13% identical).
Diseases named in the same sentence as CACUL1 in open-access papers:
CACUL1 is named in the same sentence as 8 diseases in open-access papers, as found by Europe PMC text mining. Sharing a sentence is not in itself a finding about the gene and the disease. The quoted sentences say what the papers report.
gastric cancer (5 papers, 2013 to 2023). A primary or metastatic malignant neoplasm involving the stomach. "It has also been reported that circERBB2 facilitated the progression of gastric cancer via miR-503/CACUL1 and miR-637/MMP-19 signaling." (PMID 35931993, 2022). "Li showed that upregulation of circular RNA circ-ERBB2 predicts unfavorable prognosis and facilitates the progression of gastric cancer via miR-503/CACUL1 signaling." (PMID 31249473, 2019).
colorectal cancer (1 paper, 2019). A primary or metastatic malignant neoplasm that affects the colon or rectum. "CDK2-associated cullin domain 1 (CAC1) is as a novel cell cycle regulator widely expressed in colorectal cancer (CRC)." (PMID 31504073, 2019).
Obesity (1 paper, 2017). Accumulation of substantial excess body fat. "Overall, our data suggest that CACUL1 tightly regulates PPARγ signaling through the mutual opposition between SIRT1 and LSD1, providing insight into its potential use for anti-obesity treatment." (PMID 29233982, 2017).
cancer (1 paper, 2015). A tumor composed of atypical neoplastic, often pleomorphic cells that invade other tissues. "Our data concur with these observations, as high CACUL1 levels in cancers may lead to higher Nrf2 stabilization and activity in these cells, which can be expected to contribute to cellular tolerance against stress and cell death." (PMID 26238671, 2015). "Overall, CACUL1 may be a potential target for cancer treatment." (PMID 26238671, 2015).
tumor (1 paper, 2023). "miR-199a-5p can target CAC1 (CDK2-associated cullin domain 1), a novel cell cycle regulator widely expressed in CRC, for degradation and, therefore, functions as a tumor suppressor." (PMID 36765824, 2023).
CACUL1 also shares sentences with these, for which no sentence is quoted: colon carcinoma (1 paper); gastric tumor (1); neuroblastoma (1).